KRTAP9-7 (keratin associated protein 9-7)
Description:
In the hair cortex, hair keratin intermediate filaments are embedded in an interfilamentous matrix, consisting of hair keratin-associated proteins (KRTAP), which are essential for the formation of a rigid and resistant hair shaft through their extensive disulfide bond cross-linking with abundant cysteine residues of hair keratins. The matrix proteins include the high-sulfur and high-glycine-tyrosine keratins (By similarity).
Synonyms: KAP9.7; KRTAP9L1
Tractability: No criterion of Open Targets' tractability assessment is met for any kind of drug.
Gene: Protein-coding gene on chromosome 17 (41,275,698 to 41,276,207, forward strand). Ensembl gene ENSG00000180386.
Pathways (Reactome):
Developmental Biology: Keratinization
Gene Ontology:
Cellular component: cytosol; keratin filament
Genetic constraint (gnomAD): Loss-of-function variants: 0 observed, 0.91 expected, observed/expected ratio (o/e) 0, 90% interval 0 to 1.75. That is too few expected variants to judge how well the gene tolerates losing a copy. Missense variants: 154 observed, 175.14 expected, observed/expected ratio (o/e) 0.88, 90% interval 0.77 to 1. Synonymous variants: 64 observed, 59.68 expected, observed/expected ratio (o/e) 1.07, 90% interval 0.88 to 1.32.
Homologues: Orthologues: chimpanzee KRTAP9-7 (90% identical). Paralogues in human: KRTAP9-2 (92% identical), KRTAP9-9 (92% identical), KRTAP9-3 (88% identical), KRTAP9-8 (84% identical), KRTAP9-6 (82% identical), KRTAP9-1 (80% identical), KRTAP9-4 (79% identical), KRTAP4-12 (53% identical), KRTAP4-6 (51% identical), KRTAP4-9 (50% identical), KRTAP4-11 (49% identical), KRTAP4-3 (46% identical), and 35 more.